IDSP1 (iduronate 2-sulfatase pseudogene 1)
Synonyms: IDS2
Gene: Unprocessed pseudogene on chromosome X (149,525,001 to 149,526,043, forward strand). Ensembl gene ENSG00000176289.
Diseases named in the same sentence as IDSP1 in open-access papers:
IDSP1 is named in the same sentence as 3 diseases in open-access papers, as found by Europe PMC text mining. Sharing a sentence is not in itself a finding about the gene and the disease.
IDSP1 shares sentences with these, for which no sentence is quoted: hemophilia A (1 paper); Hunter syndrome (1); iron-deficiency (1).